ERBB2 (erb-b2 receptor tyrosine kinase 2)
Diseases named in the same sentence as ERBB2 in open-access papers (continued):
Sharing a sentence is not in itself a finding about the gene and the disease.
invasive lobular carcinoma (115 papers, 2009 to 2026). "Mutations at L755 and V777 accounted for 30.5% of these mutations in ERBB2-mutated BC, suggesting that these sites are mutational hot spots in BC, particularly in invasive lobular carcinoma." (PMID 34257600, 2021). "Our results confirmed the important role of ERBB2 gain-of-function mutations in high-grade invasive lobular breast carcinoma, in agreement with previous observations." (PMID 30641862, 2019). "Previous reports suggested that ERBB2 mutations might be enriched in a specific histological subtype, invasive lobular carcinoma (ILC), which account for 5-15 % of invasive breast tumors." (PMID 27602491, 2016). "This is consistent with the known lower prevalence of HER2 expression or ERBB2 amplification in invasive lobular carcinomas and the fact that lobular carcinomas more frequently present a HER2–0 phenotype." (PMID 41040514, 2025). "Her2 (ERBB2) activating point-mutations are often detected in ER-positive carcinomas undergoing sequencing through NGS, especially in metastatic invasive lobular carcinomas (in up to 8%)." (PMID 38015260, 2024). "Our study aims to determine ERBB2 and ERBB3 mutations frequencies in grade 3 and/or ERBB2-positive invasive lobular breast carcinomas (ILC)." (PMID 27602491, 2016). "In summary, we have found that the TWIST1 mRNA expression level is associated with small tumor size, invasive lobular carcinoma, stromal-rich tumors and with PGR and ERBB2 (over)expression." (PMID 22967435, 2012). "Most invasive lobular breast carcinomas (ILBCs) are luminal‐type carcinomas with an HER2‐negative phenotype (ERBB2 or HER2 un‐amplified) and CDH1 mutations." (PMID 38335502, 2024). "Indeed, the morphology revealed the features of the original invasive lobular carcinoma (ILC), and the IHC analysis of oestrogen, progesterone, Ki67 and HER2 (c-erbB2) confirmed the molecular characteristics of the biopsy and surgical original tissue." (PMID 38926706, 2024). "In summary, IHC showed that the expression of prognostic, tumor progression, stem‐cell, and breast‐specific markers does not show major differences between ERBB2‐amplified and ERBB2‐unamplified invasive lobular carcinomas." (PMID 38335502, 2024). "Can high nodal burden (≥4 axillary metastases/≥N2) be predicted without completion axillary lymph node dissection (CALND) in patients with luminal ERBB2-negative tumors and, separately, in those with invasive lobular carcinoma, and 1 or 2 sentinel lymph node (SLN) macrometastases?" (PMID 39320882, 2024).
squamous cell carcinoma (114 papers, 2004 to 2025). A carcinoma arising from squamous epithelial cells. "They found novel somatic mutations in the MAPK1 gene (8%), HLA-B gene (9%), EP300 (16%), FBXW7 (15%), NFE2L2 (4%), and ERBB2 (6%) of 79 squamous carcinomas, and ELF3 (13%) and CBFB (8%) mutations in 24 adenocarcinomas." (PMID 26701206, 2016). "The first and only molecular analysis to identify HER2 expression and ERBB2 mutations in squamous cell carcinoma of the anal canal has been recently published." (PMID 39335117, 2024). "Interaction of SDC1 and α6β4 integrin cytoplasmic domains would regulate ErbB2-mediated integrin activation in human squamous carcinoma cells." (PMID 32756007, 2020). "An anti-ErbB2 CAR construct against HER2-positive breast, ovarian, and squamous cell carcinoma cell lines mediated improved killing ability of NK-92 cells." (PMID 25972867, 2015). "In line with previous observations, this analysis showed that both adenocarcinomas and squamous cell carcinomas exhibited upregulation of pathways controlling cell differentiation, adhesion and immune responses, along with higher expression of ERBB2 and TP63 (Q < 0.05, Methods section)." (PMID 29535388, 2018). "Squamous cell carcinomas showed frequent genic amplification of CCND1 and SOX2 and/or TP63, while ERBB2, VEGFA, GATA4, and GATA6 were more commonly amplified in adenocarcinomas." (PMID 37893095, 2023). "Squamous cell carcinomas showed frequent genomic amplifications of CCND1 and SOX2 and/or TP63, whereas ERBB2, VEGFA and GATA4 and GATA6 were more commonly amplified in adenocarcinomas." (PMID 28052061, 2017). "EGFR has been shown to initiate multistage skin carcinogenesis in murine models through activation of STAT3 and ErbB2 and EGFR family receptors have been demonstrated to be frequently amplified in squamous cell carcinoma of uterine cervix." (PMID 20977777, 2010). "To address this issue, we analyzed the capability of fUSE5-ZZ-chFRP5 complex to internalize into ErbB2 overexpressing human breast adenocarcinoma SKBR3 cells and human epidermoid carcinoma cell line A431 cells using confocal microscopy." (PMID 18387177, 2008). "As a negative control, we used A431 cells (from human epidermoid carcinoma), which express very low levels of ErbB2." (PMID 21559015, 2011). "It did not react instead with ErbB2-negative cells such as A431 cells (from human epidermoid carcinoma), which overexpress the ErbB1 EGF receptor from the same ErbB family." (PMID 15305184, 2004).
metastatic carcinoma (112 papers, 2010 to 2025). A carcinoma which has spread from the original site of growth to another anatomic site. "ErbB2 is a potent oncogene whose overexpression is notoriously associated with invasive and metastatic cancer." (PMID 24709902, 2014). "The mutations were concordant between the primary and metastatic carcinomas in all, except for the ERBB2 case, where the primary carcinoma had the mutation, while the corresponding metastasis showed no detectable mutations, possibly due to sampling bias or tumor heterogeneity." (PMID 40423053, 2025). "Axillary lymph node biopsy showed metastatic carcinoma with IHC: ER 90% (3+), PR 90% (3+), HER2 (c-erbB-2) 1+, Ki-67 20%, and AR 90% (3+)." (PMID 40548112, 2025). "Currently, this treatment regimen is available in the clinic as a first-line therapy for patients with metastatic cancer of the stomach or gastroesophageal junction (GEJ) positive for ERBB2 protein (also called HER2)." (PMID 26267324, 2015). "This information could be useful in patient treatment when anti–ERBB2-low therapy is considered and the patient has metastatic carcinoma with the primary tumor being mucin-producing or metaplastic BC." (PMID 38517439, 2024). "Acquired alterations have been reported in FGFR4 and ERBB2/HER2 upon metastatic cancer progression." (PMID 30903103, 2019). "In addition to inducing very aggressive, metastatic cancer, ErbB2 activation mediates processes such as increased cancer cell proliferation and survival and is needed for normal physiological activities, such as heart function and development of the nervous system." (PMID 24709902, 2014). "NOTCH2, NOTCH2NL, KIF5B, and ERBB4 are highly expressed in primary cancer, while ERBB2, CLDN11 and CDK12 are overexpressed in metastatic cancer." (PMID 33441952, 2021). "Population-wide comparison between TT and LN single cells revealed that NOTCH2, NOTCH2NL, KIF5B, and ERBB4 are highly expressed in primary cancer, while CDK12, ERBB2, and CLDN11 are overexpressed in metastatic cancer." (PMID 33441952, 2021). "Over-expression of the human erb-b2 receptor tyrosine kinase 2 (ERBB2) marks the acquisition of growth factor independence by primary and metastatic cancers, and dictates therapeutic ERBB2 blockade by small drugs and antibodies." (PMID 28817097, 2017). "The HER2 protein, which is upregulated as a result of high-level ERBB2 amplification, is a druggable target, and the HERACLES trial demonstrated a 30% response rate to dual HER2 blockade in the 5% subpopulation of HER2 positive and KRAS wild-type metastatic cancers." (PMID 31308487, 2019). "Noticeably, T-DM1, a maytansinoid conjugated to Trastuzumab was approved specifically for the treatment of ErbB2/HER2-positive metastatic cancer, indicating the potential benefit of targeting this novel MTA binding site." (PMID 26497677, 2015).
Obesity (112 papers, 2005 to 2026). Accumulation of substantial excess body fat. "Molecular docking results also revealed that the hub target genes bound to melatonin with high affinity, particularly AKT1, PTGS2, and ERBB2, can be used to treat LR-induced obesity by melatonin." (PMID 35937803, 2022). "Reports were generated on a number of key areas including DNA repair, hormone-related pathways, ERBB2/HER2, PI3K/AKT/mTOR signaling, the ubiquitin-ligase complex, the WNT pathway, the immune system, and obesity-driven targets." (PMID 29137450, 2017). "IFI16, ERBB2, VIM (vimentin) and CAV1 are crucial factors for advancement of obesity." (PMID 36837510, 2023). "Through molecular classification, several target genes and molecular pathways in this tumor were identified, including DNA repair, hormone-related pathways, ERBB2/HER2, PI3K/AKT/mTOR signaling, the WNT pathway, immune-related pathways and obesity-driven targets." (PMID 30181460, 2018).
metastatic colorectal cancer (102 papers, 2009 to 2026). "The US Food and Drug Administration-approved anti-HER2 tucatinib plus trastuzumab treatment for chemotherapy-refractory ERBB2 (HER2)-positive RAS-wild type metastatic colorectal cancer has shown favorable outcomes." (PMID 41413856, 2025). "Overall, we report a case of a female patient with refractory metastatic colorectal cancer harboring ERBB2 amplification." (PMID 40051563, 2025). "Of note, in a study of 57 patients with metastatic colorectal cancer and ERBB2 amplification, despite an overall objective response rate of 32%, none of the 8 patients with amplification without HER2 overexpression responded to trastuzumab and pertuzumab." (PMID 35126865, 2022). "Concurrently targeting Notch and Erbb2 pathways in metastatic colorectal cancers that were resistant to cetuximab resulted in antitumor response, suggesting dependence of tumor on Notch and Erbb2." (PMID 32211044, 2020). "This fatal occurrence was reported in a patient with metastatic colorectal cancer following the administration of ERBB2 CAR-Ts where low expression of ERBB2 on respiratory normal epithelial cells led to acute pulmonary manifestation and the patient’s death 5 days after the injection of CAR-Ts." (PMID 29844297, 2018). "Recently, next-generation sequencing (NGS) discovered ERBB2 as a promising therapeutic target in metastatic colorectal cancer (mCRC), where it is altered in 3–5% of patients, but no therapies are currently approved for this use." (PMID 38138928, 2023).
hepatocellular carcinoma (101 papers, 2006 to 2025). A malignant tumor that arises from hepatocytes. "In our study, we sought to determine if similar respective gain-of-function EGFR and ERBB2 mutations were present in hepatoma and biliary cancers to determine the potential for ERBB -targeted therapy." (PMID 17150109, 2006). "In our study, we sought to determine if similar respective gain-of-function EGFR and ERBB2 mutations were present in hepatoma and/or biliary cancers." (PMID 17150109, 2006). "Recently, it has also been found that acquired resistance toward Infigratinib in hepatocellular carcinoma correlates with higher phosphorylation levels of ERBB2/3 and increased EZH2 expression." (PMID 38177929, 2024). "It has been predicted via bioinformatic analysis and confirmed by chromatin immunoprecipitation analysis that in hepatocellular carcinoma cells the promoter of ERBB2 binds to the transcription factor NKX2-5, resulting in a negative regulatory effect." (PMID 36612126, 2022). "ErBb2 is strongly upregulated in hepatitis B-infected livers and has been suggested as an early marker of hepatocellular carcinoma." (PMID 35154607, 2021). "Mir-375 upregulates cell proliferation and apoptosis by targeting ERBB2 and inhibits the growth of human hepatoma cells." (PMID 32963562, 2020). "Rapamycin also inhibits angiogenic responses in ErbB2 transgenic mouse mammary, human hepatocellular carcinoma, and in corneal neovascularization models presumably by suppression of Akt-dependent HIF-1 signaling." (PMID 18570671, 2008). "ERBB2 is also expressed in a significant number of hepatoma and biliary cancers acting as an independent prognostic factor and a major contributor to carcinogenesis." (PMID 17150109, 2006). "The ERBB2 oncogene hypothesis is challenged in hepatocellular carcinoma (HCC) with the conflicting evidences of human epidermal growth factor receptor 2 (HER2) overexpression." (PMID 30714677, 2019). "In this TDCC assay, the effector cells were spleen cells of human CD3 EDG–replaced mice and the target cells were Hepa1-6/hGPC3/HER2 cells, in which human glypican-3 (GPC3) and erb-b2 receptor tyrosine kinase 2 (HER2) are significantly expressed in Hepa1-6 mouse hepatocellular carcinoma." (PMID 28368009, 2017). "We found 11% of hepatoma, but no biliary cancers, harbored a novel ERBB2 H878Y mutation in the activating domain." (PMID 17150109, 2006). "In hepatocellular carcinoma (HCC), ErbB2 overexpression is uncommon." (PMID 32591879, 2021). "In contrast, 2 (11%) of the 18 hepatoma had a single novel somatic H878Y (CAT to TAT; c.2632C > T) mutation in exon 21 of ERBB2, while none of the biliary cancers were found to have somatic mutations." (PMID 17150109, 2006). "In previous studies, Erb-B2 receptor tyrosine kinase 2 (ERBB2) and NUF2 component of the NDC80 Kinetochore Complex (NUF2) were reported to be biomarkers of hepatocellular carcinoma (HCC) recurrence after surgery." (PMID 34956309, 2021). "Experiments were performed using three hepatocellular carcinoma (HCC) cell lines, Hep3B, HepG2 and PLC/PRF/5, expressing various levels of EGFR, ErbB2 and ErbB3." (PMID 32515546, 2020). "Also, ERBB2, c-myc, and RAS were positive in 86% (12/14) of hepatocellular carcinoma (HCC) patients, and c-myc and Ras have a direct correlation with bile duct malignancy and morphogenesis." (PMID 32708604, 2020).
urothelial carcinoma (101 papers, 2009 to 2026). A malignant neoplasm derived from the transitional epithelium of the urinary tract (urinary bladder, ureter, urethra, or renal pelvis). "One patient in the urothelial carcinoma cohort (5%) was found to have an activating mutation in ERBB2." (PMID 40767528, 2025). "Recently, lower prevalence of ERBB2 copy number variant was observed in HER2 protein overexpressing canine urothelial carcinoma." (PMID 32059046, 2020). "HER2, encoded by the ERBB2 gene, is an important druggable driver of human cancer gaining increasing importance as a therapeutic target in urothelial carcinoma (UC)." (PMID 38908022, 2024). "Differences in gene expression and mutational profile were also seen in urothelial carcinoma, which is characterized by overexpression of EGFR and ERBB2 in approximately 70% and 60% of the tumors, respectively, and clinical response to EGFR/ERBB2 inhibitors." (PMID 37414794, 2023). "The genomic, transcriptomic, and immunologic landscapes of urothelial carcinoma based on ERBB2 expression were investigated." (PMID 38136267, 2023). "ERBB2 and BRAF are the most frequently mutated genes in pulmonary adenocarcinoma and urothelial carcinoma, mutated in 50% and 40% of the samples respectively." (PMID 37414794, 2023). "The present study demonstrates a high concordance between the immunohistochemistry (IHC) expression of HER2 and the RNA expression of ERBB2 in urothelial carcinoma." (PMID 38136267, 2023). "Her-2/ERBB2 gene is one of those targets of interest which is largely been assessed for its role in the treatment of urothelial carcinoma." (PMID 35509755, 2022). "Several studies have also reported a low concordance between ERBB2 protein level and gene amplification in urothelial carcinomas." (PMID 28388586, 2017). "In urothelial carcinomas, overexpression of ERBB2 protein has been reported to vary considerably between studies as well as between geographically distinct cohorts." (PMID 28388586, 2017). "In analogy with other tumor types, members of the ERBB receptor family have been considered as potential targets also for urothelial carcinomas e.g., ERBB2 (HER2) and EGFR." (PMID 28388586, 2017). "The epidermal growth factor receptor (EGFR) tyrosine kinase family comprises four members (erbB-1 through erbB-4), with erbB-1 (EGFR) and erbB-2 (Her2/neu) expressed in urothelial carcinoma." (PMID 19918289, 2009). "ERBB2 fusion combined with amplification was found in patients with lung, colorectal, gastric, liver, biliary tract, breast, esophageal, and gastroesophageal junction cancers and urothelial carcinoma." (PMID 36276102, 2022). "The association with kidney carcinomas is novel in this analysis, but may be due to the fact that a number of urothelial carcinomas express Erbb2 (also known as Her2neu), which interacts with EGFR and may introduce genetic instability leading to high cancer maximum multiplicity in this analysis." (PMID 21714919, 2011). "Here we investigate EGFR, ERBB2 (HER2), and ERBB3 (HER3) genomic alterations and expression in relation urothelial carcinoma molecular subtypes." (PMID 28388586, 2017). "To clarify the molecular context in which ERBB2 and EGFR gene amplifications and overexpression occur we performed an in-depth study of EGFR, ERBB2, and ERBB3 alterations in relation to existing urothelial carcinoma molecular subtypes." (PMID 28388586, 2017). "We analyzed a cohort of 599 cases of urothelial carcinoma for EGFR, ERBB2, and ERBB3 gene expression and genomic alterations." (PMID 28388586, 2017). "The functional crosstalk between ErbB2 and EMP3 activated the ErbB2-PI3K-AKT pathway to promote cancer cell proliferation and migration in urothelial carcinoma." (PMID 27527869, 2017). "Potentially actionable genomic alterations included FGFR2/3, ERBB2, and PIK3CA, and alteration frequencies of these genes in resected MIBC from IMvigor010 were similar to the prevalence in advanced-stage urothelial carcinoma based on the FoundationCORETM dataset." (PMID 37601688, 2023).
urothelial carcinoma (continued). "In essence, urothelial carcinomas could be divided into two distinct categories based on EGFR, ERBB2, and ERBB3 expression and genomic alterations." (PMID 28388586, 2017).
metastasis (97 papers, 2008 to 2026). The spread or migration of cancer cells from one part of the body (where they first appeared) to another. "We found that ERBB2 and HOXB-AS3 genes were more amplified in metastasis tumors than in primary tumors." (PMID 35935940, 2022).